IL1B (interleukin 1 beta)
Diseases named in the same sentence as IL1B in open-access papers (continued):
Sharing a sentence is not in itself a finding about the gene and the disease.
pneumonia (continued). "Notably, differences in the ROR values among different drugs further highlight the mechanistic nuances: canakinumab, a selective IL-1β neutralizer, reported data on pneumonia with an ROR of 2.3 (95% CI: 2.07–2.56), whereas neither anakinra nor rilonacept reported an ROR for this event." (PMID 41471316, 2025). "Host factors CRP, IL-1β, hs-CRP, IL-8, and IL-6 levels in severe pneumonia patients were higher than in non-severe patients." (PMID 33065551, 2020). "By comparing the hub genes with the top ten genes of pneumonia, we found 5 overlapping genes (IL-1B, IL-6, CXCL8, TNF, and IL-10), which might interpret on how the YPFG exerts a therapeutic effect in some types of pneumonia but not all types of pneumonia." (PMID 36285159, 2022). "Although the concentrations of IL-13, IL-17A, MIP-1α/CCL3, PAI1, sCD14, IL-1β, CCL11/eotaxin, VEGF/VPF, and RANTES/CCL5 did not exhibit significant differences between the HIV and pneumonia and HIV-only groups, several reasons could explain this lack of disparity." (PMID 38251391, 2024).
schizophrenia (171 papers, 2011 to 2026). A major psychotic disorder characterized by abnormalities in the perception or expression of reality. "The severity of psychopathology in patients with schizophrenia seems associated with higher levels of IL-1β and lower levels of BDNF." (PMID 41010622, 2025). "Neuroinflammatory processes are also implicated in the pathophysiology of schizophrenia, where microglia in these patients show increased expression of pyroptosis-related genes and reduced responsiveness to IL-1β treatment." (PMID 39859234, 2025). "Studies show that schizophrenia is associated with elevated levels of pro-inflammatory factors, particularly IL-1β (interleukin 1 beta), IL-6 (interleukin 6), IL-8 (interleukin 8) and TNF-α (tumor necrosis factor alpha-like)." (PMID 39859234, 2025). "A cross-sectional study found that higher level of IL-1β was associated with higher resistance subscale scores in patients with first-episode schizophrenia." (PMID 38352871, 2024). "IL-1β and its single nucleotide polymorphisms are implicated in white matter and gray matter volume abnormalities in schizophrenia." (PMID 37946206, 2023). "A more recent study also suggested that brain volume loss in schizophrenia is associated with a genetic predisposition to produce more IL-1β." (PMID 33667853, 2021). "Allelic or genotypic association between the IL-1β C-511T polymorphism and schizophrenia was reported by case-control as well as family studies." (PMID 33746786, 2021). "In patients with schizophrenia, presence of gene polymorphisms of proinflammatory cytokines, such as IL-1β and IL-6, have been linked to high serum levels of these cytokines." (PMID 33746786, 2021). "The decreased IL-1β-induced CCL20 secretion by schizophrenia iPSC-astrocytes cause potential attenuating effects on recruitment of Tregs." (PMID 32802190, 2020). "The underlying mechanisms for the decreased TNF-α and IL-1β levels in FEDN patients with schizophrenia should be further investigated." (PMID 29867314, 2018). "In terms of symptomatology, elevated IL-1β in the schizophrenia sample was linked to increased positive symptoms on the SAPS." (PMID 29803226, 2018). "Increased IL-1β mRNA levels in leukocytes in patients with schizophrenia have also been linked to decreased Broca’s area volume and poorer verbal fluency." (PMID 29803226, 2018). "Recent meta-analyses of case control studies investigating cytokine genes, indicates polymorphisms in IL-1β, IL-6, and soluble IL-6 receptors (sIL6R) are also associated with risk for schizophrenia." (PMID 28396623, 2017). "A study investigating a population of carriers of the NRG1 (valine to leucine) mutation has observed increased circulating proinflammatory cytokines, including IL-6, TNF-α, and IL-1b suggesting a role of this mutation in immune dysregulation in schizophrenia." (PMID 23805069, 2013). "Several lines of evidence suggest that pro-inflammatory cytokine interleukin-1beta (IL-1β) is implicated in the etiology and pathophysiology of schizophrenia." (PMID 21843369, 2011). "Although our male sample was not large enough to detect a small relative risk, our data suggest that susceptibility to schizophrenia is more influenced by the IL-1β gene variation in females." (PMID 21843369, 2011). "Five tagging polymorphisms of IL-1β gene (rs2853550, rs1143634, rs1143633, rs1143630, rs16944) were examined for association with schizophrenia." (PMID 21843369, 2011). "Three studies in Caucasian populations reported a significant association of schizophrenia with an IL-1β gene polymorphism rs16944." (PMID 21843369, 2011). "Several lines of evidence have implicated the pro-inflammatory cytokine interleukin-1beta (IL-1β) in the etiology of schizophrenia." (PMID 21843369, 2011). "We here examined 5 tagging polymorphisms of the IL-1β gene for an association with schizophrenia in a Japanese sample." (PMID 21843369, 2011).
schizophrenia (continued). "The present study shows the first evidence that the IL-1β gene polymorphism rs1143633 is associated with schizophrenia susceptibility in a Japanese population." (PMID 21843369, 2011). "Indeed, genetic studies have demonstrated changes in the IL1B gene in schizophrenia and a significant association of the IL1B gene polymorphisms with the risk of schizophrenia and age of onset." (PMID 41010622, 2025). "Notably, elevated serum levels of IL-1β (interleukin 1 beta) in schizophrenia, a cytokine associated with inflammation, are a characteristic feature of pyroptosis—a form of pro-inflammatory programmed cell death." (PMID 39859234, 2025). "It was suggested that IL-1β may be found as a state marker linked with the intensity of schizophrenia symptoms." (PMID 40364201, 2025). "Similarly, previous studies have shown that MD was associated with elevated level of IL-1β both in the general population and in patients with schizophrenia." (PMID 39831058, 2024). "Notably, this study represents the first prediction of the interactions of IL-1α, IL-1β, and IL- 1RA proteins, taking into account the presence of single-nucleotide polymorphisms associated with schizophrenia in the sequence of the corresponding genes." (PMID 38988763, 2024). "Furthermore, elevated levels of peripheral cytokines such as IL-1β are found in some patients with schizophrenia and are associated with neurocognitive impairment." (PMID 39902241, 2024). "Animal models also suggest that the presence of schizophrenia-like behaviors may be associated with increased IL-1β levels." (PMID 37270510, 2023). "Since schizophrenia is related to a dysfunction of dopaminergic and glutamatergic brain circuits, it has been argued that IL-1β may causally link inflammatory processes to dopaminergic/glutamatergic dysfunctions." (PMID 35963926, 2022). "Furthermore, schizophrenia in a Japanese population study was significantly associated with IL-1β SNPs (C-373T, C-1473T, and C-511T)." (PMID 33746786, 2021). "Based on the direction of the IL1B allele effects on schizophrenia risk, we hypothesized that the variant C of IL1B would potentiate the development of schizotypal traits in individuals born during winter." (PMID 29464121, 2017). "Furthermore, none of the previous studies in Asian populations have obtained evidence for an association between IL-1β gene and schizophrenia." (PMID 21843369, 2011). "The results suggest the possibility that the influence of IL-1β gene variations on susceptibility to schizophrenia may be greater in females than in males." (PMID 21843369, 2011). "Taken together with our results, the influence of IL-1β on susceptibility to schizophrenia may differ between genders." (PMID 21843369, 2011). "Our results suggest that rs1143633 of IL-1β gene is associated with schizophrenia susceptibility in a Japanese population and that the influence of IL-1β gene variations on susceptibility to schizophrenia may be greater in females than in males." (PMID 21843369, 2011). "A number of genetic association studies have suggested that genetic variation of the IL-1β gene might confer susceptibility to schizophrenia." (PMID 21843369, 2011). "Furthermore, not only IL-1β was involved in abnormalities in the volume of white matter and gray matter in the brain of schizophrenia, but also associated with speech fluency and decreased Broca region volume in schizophrenia." (PMID 37946206, 2023). "For IL-1β effects, future studies looking at different developmental time points and cell types could elucidate this cytokine’s role in neurodevelopmental processes associated with schizophrenia." (PMID 35716830, 2022). "Also, the IL-1β rs16944 polymorphism has been associated with reduced hippocampal volume, white matter and bilateral frontotemporal grey matter deficits as well as and ventriculomegaly in patients with schizophrenia ⁠." (PMID 32495042, 2021).
schizophrenia (continued). "Some studies have proved that heightened stress is immunosuppressive, and thus, the decreased TNF-α and IL-1β in our current study may be caused by stress in first episode schizophrenia, since the experience of acute psychosis in schizophrenia patients is stressful itself." (PMID 29867314, 2018). "Existing literature suggests that the effect of winter birth on schizophrenia risk might be mediated by increased expression of the proinflammatory cytokines, in particular, IL-1β, due to prenatal infection and its inadequate regulation by anti-inflammatory factors." (PMID 29464121, 2017). "The authors reported a greater monocytic expression of IL-1β in persons with schizophrenia than in HCs in an unstimulated state." (PMID 40153412, 2025). "Our clinical observations revealed that the levels of CASP1, GSDMD, and IL1B were significantly elevated in the blood of patients with schizophrenia and positively correlated with HERV-W env." (PMID 39859234, 2025). "Increased concentrations of IL-1β, IL-6, IL-10, IL-17, sIL-2R, and IL-33, but also decreased concentrations of TNF-α, were similarly associated with more severe positive symptoms of schizophrenia." (PMID 40364201, 2025). "The elevation of pro-inflammatorybiomarkers such as IL-6, IL-1β, TNF-α, and CRP has beenassociated with cognitive decline, with this association being particularlypronounced in patients with deficit schizophrenia." (PMID 40926813, 2025). "The data on IL-1β are consistent with a meta-analysis from 2023 (patients diagnosed with schizophrenia n = 430, and healthy controls n = 346) and with later studies." (PMID 41010622, 2025). "In summary, our results confirm the presence of immune disequilibrium between IRS and CIRS systems in TRS patients and the potential role of IL-1β in development of drug-resistant schizophrenia." (PMID 40364201, 2025). "Elevated concentrations of cytokines such as interleukin-6 (IL-6), tumor necrosis factor-alpha (TNF-α), and interleukin-1 beta (IL-1β) have been repeatedly observed in individuals with schizophrenia." (PMID 40635756, 2025). "Previous research has observed significant upregulation of pyroptosis-related genes, such as CASP1, NLRP3, and IL1B, in the serum of schizophrenia patients." (PMID 39859234, 2025). "The inflammatory biomarkers most frequently associated with CT are CRP, IL-1β, IL-6, and TNF-α, parameters which have also been found to be elevated in schizophrenia." (PMID 41049865, 2025). "As in ASD, patients with schizophrenia exhibit elevated levels of proinflammatory cytokines, such as IL-1β, IL-6, and TNF-α, alongside reduced levels of anti-inflammatory cytokines, including IL-10, IL-1β, and IL-8, when compared to healthy individuals." (PMID 40276707, 2025). "In this study, we found that the expression levels of pyroptosis-related genes, specifically CASP1, GSDMD (Gasdermin D), and IL1B, were significantly elevated in patients with schizophrenia compared to healthy controls." (PMID 39859234, 2025). "Clinical studies have shown elevated levels of CASP1, GSDMD, and IL1B in the blood of schizophrenia patients, highlighting their role in the classical pyroptosis pathway." (PMID 39859234, 2025). "Our clinical data showed that pyroptosis-related genes, including CASP1, GSDMD, and IL1B, were significantly elevated in patients with schizophrenia and positively correlated with HERV-W env expression." (PMID 39859234, 2025). "Our clinical findings indicate a strong association between HERV-W env and the pyroptosis-related genes CASP1, GSDMD, and IL1B in individuals with schizophrenia." (PMID 39859234, 2025). "BDNF binding to TrkBTK- receptors on glia can promote the release of pro-inflammatory cytokines, including IL1β and TNFα, consistent with the increase of these cytokines at the mRNA and protein level we have found in the schizophrenia midbrain." (PMID 40335479, 2025).
schizophrenia (continued). "Shirts B.H., Wood J., Yolken R.H., Nimgaonkar V.L. Association studyof IL10, IL1β, and IL1RN and schizophrenia using tag SNPs froma comprehensive database: suggestive association with rs16944 atIL1β." (PMID 38988763, 2024). "NFκB is a master immune transcription factor, which regulates inflammatory cytokines, including IL-1β, IL-6, and TNFα, and is involved in the pathogenesis of schizophrenia." (PMID 39769285, 2024). "Serum IL-1β levels in first-episode schizophrenia and serum IL-16 levels in relapsing schizophrenia were correlated with the parts of psychiatric symptoms." (PMID 37270510, 2023). "The role of NLRP3, Caspase 1, and IL-1β in the pathological process of schizophrenia deserves further investigation." (PMID 37946206, 2023). "Particularly at the onset of schizophrenia and during the recurrence of psychotic episodes, blood levels of proinflammatory cytokines such as IL-1β, IL-6, and TNF-α tend to increase, and levels of IL-6 are associated with poor schizophrenia prognosis." (PMID 37371435, 2023). "Our results show that the expressions of miR-3653-3p in the peripheral blood of patients with acute schizophrenia were lower, which was first reported in schizophrenia, and the relative expressions of caspase 1 mRNA and IL-1β mRNA were all elevated." (PMID 37946206, 2023). "Polymorphic variants of the IL1B, IL6, IL6R, IL10, IL17A, and TNFA genes have been associated with schizophrenia." (PMID 37510364, 2023). "Previously, differentially expressed prefrontal cortex NLRP3, Caspase 1, and IL-1β have been reported in post-mortem brains of schizophrenia patients." (PMID 37946206, 2023). "Plasma IL-1β of first-episode schizophrenia and plasma IL-16 of relapsing schizophrenia were correlated with the parts of psychiatric symptoms." (PMID 37270510, 2023). "An increased level of IL-1β, as a pro-inflammatory cytokine, can lead to inflammation in the first episode of schizophrenia; therefore, the evidence provides new information on monocytes’ over-activation in schizophrenia." (PMID 37644489, 2023). "A previous study suggested that proinflammatory cytokine (IL-1β, IL-6, IL-8, and TNFα) release was enhanced in whole blood from schizophrenia patients." (PMID 37210391, 2023). "In previous studies, as a crucial proinflammatory cytokine, IL-1β was recognized as a signature molecule and differentially expressed in peripheral blood and cerebrospinal fluid of schizophrenia; whether IL-1β is a cause or an effect of schizophrenia is unknown." (PMID 37946206, 2023). "Significant increases in IL-1β during acute exacerbation of chronic schizophrenia have been reported before." (PMID 37946206, 2023). "Plasma IL-1β levels in patients with first-episode schizophrenia were significantly higher than those in patients with relapsing schizophrenia and healthy subjects." (PMID 37270510, 2023). "In conclusion, the levels of IL-1β and IL-16 are different between patients with schizophrenia and healthy subjects." (PMID 37270510, 2023). "The expression of miR-3653-3p, NLRP3, caspase 1, and IL-1β in schizophrenia does show interconnection." (PMID 37946206, 2023). "We also found an increase in the serum levels of IL-1β in patients with schizophrenia, which is also confirmed by a number of studies." (PMID 37239308, 2023). "Among them, IL-1β has repeatedly been shown to be elevated in the peripheral blood and cerebrospinal fluid of patients with schizophrenia." (PMID 37946206, 2023). "At last, we found an association between IL-1β and the chronic course of schizophrenia; this indicates that IL-1β is involved in the chronic course of schizophrenia." (PMID 37946206, 2023). "This is particularly interesting given that patients in our cohort had higher levels of IL-1β transcript in the blood, and several studies have found elevated IL-1β protein in the blood in people with schizophrenia compared to controls." (PMID 35027554, 2022).